FGFR1 (fibroblast growth factor receptor 1)
Diseases named in the same sentence as FGFR1 in open-access papers (continued):
Sharing a sentence is not in itself a finding about the gene and the disease.
tumor (continued). "Fibroblast growth factor receptor 1 (FGFR1) induces the phosphorylation of PKM2 at tyrosine (Tyr) residue 105, resulting in a decrease in lactate production while promoting the induction of tumor cell growth." (PMID 27340866, 2016). "bFGF is able to bind FGFR1, FGFR2, and FGFR3, leading to auto-phosphorylation of intracellular tyrosine residues, which are involved in instigating tumor cell proliferation and invasion in various tumor types." (PMID 26824699, 2016). "Results show no significant overall correlations between FGFR1-3 IIIb/IIIc variants and expression of ESRPs in the studied CRC tumor tissue." (PMID 27650542, 2016). "However, only FGFR1 was expressed at high level, with a mean transcript expression of 187 RPKM in NRH-LS1 (and 143 in tumor B), compared to 0.3, 47, and 7.9 for FGFR2, FGFR3 and FGFR4, respectively." (PMID 27409346, 2016). "Given the highly context-dependent and cell-type-specific nature of FGFR1 signaling, and its interaction with SPRY2 and other RTKs as we have observed, its function may change drastically during neoplasia development." (PMID 27046834, 2016). "FGFR1 was not regulated in LS180 compared to SW480 cells indicating a tumor cell type dependent mechanism of IIIb/IIIc splice regulation by ESRP1." (PMID 27650542, 2016). "Due to limited material, we were not able to investigate the subcellular localization of FGFR1 in the tumor samples." (PMID 27685995, 2016). "FGFR1 amplification was not correlated with prognosis or any other clinical variables, including gender, age, tumor site, American Joint Committee on Cancer (AJCC) staging, tumor recurrence, or metastasis." (PMID 26993773, 2016). "Given the critical importance of FGFR1 in the pathogenesis and development of NSCLC, this study identified two novel, non-ATP-competitive inhibitors of FGFR1 kinase, i.e., Ad23 and Af23, both of which exhibited good anti-tumor activity in vitro and in vivo." (PMID 25880284, 2015). "Af23 and Ad23 also showed significant anti-tumor activity in the H460 xenograft mouse model, accompanied with the inhibition of FGFR1, ERK, and AKT phosphorylation without exhibiting toxicity." (PMID 25880284, 2015). "Treatment with ARPCA efficiently inhibited FGFR1 phosphorylation, Ki67+ proliferation index and CD31+ neovascularization in tumor grafts when compared to lesions harvested from ARPVA-treated animals, thus confirming the inhibitory effect of ARPCA on in vivo S115 cell growth and angiogenic potential." (PMID 25912421, 2015). "This suggests that targeting FGFR1 alone was not sufficient to eradicate the residual Wnt1/iFGFR1 tumor cells." (PMID 26581390, 2015). "Amplification of other FGFRs has not been found in GC; however, overexpression of FGFR1 and FGFR4 or single nucleotide polymorphism of FGFR4 appears to be associated with tumor progression or survival." (PMID 26000013, 2015). "At this time, molecular profiling of the patient primary tumor was performed and it revealed FGFR1 overexpression, SOX2 amplification and no PDGFRA amplification." (PMID 25126591, 2014). "Sorafenib (SO) is an oral multikinase inhibitor, which targets several tyrosine kinases receptors (RTK), such as VEGFR2 and VEGFR3, PDGFRβ, fibroblast growth factor receptor 1 (FGFR1), and Flt-3, RET, and c-Kit, all involved in tumor growth progression and neoangiogenesis." (PMID 24527434, 2014). "In the current study, FGFR1 and MET amplifications were restricted to the EGFRwt/KRASwt tumor group, and were mutually exclusive (MET amplification was borderline non-significant for difference in frequency between mutation groups, p=0.09, Fisher’s exact test)." (PMID 24205279, 2013). "Treating shR2 tumor-bearing mice with the FGFR inhibitor PD173074 reversed the increase in proliferation and angiogenesis to the level of control shLacZ tumors, suggesting that high FGFR1 signaling in shR2 tumors plays a crucial role in all of these responses." (PMID 23185502, 2012).
tumor (continued). "As expected, neither mutant FGFR3 or upregulated FGFR1 was sufficient alone to confer on normal urothelial cells a fully transformed phenotype, such as anchorage-independent growth or the ability to form tumours in nude mice." (PMID 22899908, 2012). "Fibroblast growth factor receptor-1 (FGFR-1, CD331) is a high affinity receptor for basic fibroblast growth factor (bFGF, FGF2) and the signal transduction pathway induced by the bFGF/FGFR-1 interaction has an important role in stimulating tumor angiogenesis." (PMID 21385454, 2011). "Although these effects were not mediated via direct effects of E7080 on tumor cells two of the main targets of E7080, FGFR-1 and PDFGR, are expressed in a number of solid tumors." (PMID 21781317, 2011). "FGF2 did not correlate with the clinical variables while low FGFR-1 expression correlated with small tumor size (low expression; < 50 mm 44%, 50-100 mm 34%, > 100 mm 22%, P = 0.005)." (PMID 21733164, 2011). "E7080 shows anti-tumor activity in human cancer cell xenografts, which has been attributed to its ability to inhibit angiogenesis predominantly through effects on VEGFR-2 inhibition but also through inhibition of KIT and FGFR-1." (PMID 21781317, 2011). "On the opposite, EphB4, FGFR1, Tie2, Alk5, TNFR2, and the adhesion molecules VCAM-1 and ICAM-1 were more frequently detected and at higher levels in normal kidney endothelium as compared to tumor endothelium from intermediate and large tumors." (PMID 22235379, 2011). "FGFR1 is upregulated in GBM and is expressed by both the tumor cells and the tumor ECs." (PMID 20379377, 2010). "The aneuploidic increases in copy number of genes that may promote tumor formation, including ARHGAP26, GRB10, DDHD2, FGFR1, CTNNA3, PTPN1 and MLLT1 in the apparently stable and karyotypically normal lines HS293 and HS401, are cause for concern." (PMID 20428235, 2010). "In tumours with strong FGFR1 expression but weak or absent Sef levels, 71% had evidence of bone metastasis." (PMID 19888221, 2009). "Unlike FGFR1, these genes had high levels of differential expression between nontumor and tumor samples, which appeared to impact their AS scores." (PMID 18474104, 2008). "The anti-tumor effects can be attributed to the antiangiogenic effects of the substance, which are mediated by the inhibition of the receptor tyrosine kinases Flk-1/KDR (VEGR2), PDGFRbeta and FGFR1." (PMID 17367541, 2007). "In the human PDAC patient tumor transcriptome (TCGA), we identify strong and significant correlations between tumoral GHR expression and known lymphangiogenic (LYVE1, FLT4, VEGFC, and PDPN) and angiogenic (PDGFRa, FGFR1, TGFB3, TGFB1, TGFBR2, HIF1a, IL6, and IL1B) markers." (PMID 39000545, 2024). "We have not tested whether different FGFR1 isoforms are expressed in the tumor mass versus invasive cells, and this warrants further investigation." (PMID 37579831, 2023). "Recently, we and others have described single cases or small studies of tumours with concomitant alterations of H3-K27M and mitogen-activated protein kinase (MAPK) pathway showing a possible longer survival compared to patients with DMG H3 K27-altered, BRAF and FGFR1 wild-type." (PMID 38066305, 2023). "Similarly, tumor suppressor miR-497 could impact erlotinib resistance via modulating expression levels of fibroblast growth factor 2 (FGF2) and fibroblast growth factor receptor 1 (FGFR1)." (PMID 37560164, 2023).
tumor (continued). "Additionally, we observed that mATC cells overexpressed receptors such as FGFR1, EPHB2, PDGFRA, NOTCH3, ANTXR1, and NRP1, which could receive signals from CAFs and thereby promote tumor cell proliferation and aggressiveness." (PMID 37053016, 2023). "Therefore, as CSF1 and FGF signals are both involved in the accumulation of tumor- promoting M2 macrophages, MDSCs, and Tregs, the dual inhibition of CSF1R and FGFR1 by sulfatinib may be more effective for cancer therapy than selective CSF1R inhibition." (PMID 37361567, 2023). "Moreover, the difference between FGFR1–4 expression levels in primary tumors and tumor-adjacent normal tissues, as well as the predictive value of FGFR1–4 mRNA expression, was investigated." (PMID 36142417, 2022). "On the other hand, the presence of a MAPK pathway alteration, such as FGFR1 or BRAF mutations, may open up additional possibilities of targeted therapies, independent of the tumor classification." (PMID 33433639, 2021). "However, in mice injected with FGFR1-silenced MDA-MB-231-R cells, there was a significant reduction in tumor growth rate as compared to mice injected with the vehicle (PBS) only, for up to 30 days post tumor implantation." (PMID 33916323, 2021). "Combination treatment with ARS-1620 and AZD4547, an FGFR1 inhibitor, for 3 days showed cytotoxic effects on H358 cells that were comparable to those of ARS-1620 treatment alone; however, this treatment exhibited an enhanced tumor cell-killing effect on H23 and Calu-1 cells." (PMID 34858498, 2021). "In clinical trials, a 6-fold copy number of FGFR1 and a 4-fold copy number of FGFR2 have been used as inclusion criteria for an expected high FGFR expression status, and these patients typically showed responses to FGFRi treatment as indicated by decreased tumor growth." (PMID 33119860, 2021). "As previously reported, multiplex sequencing of tumour samples from patients with gastroesophageal cancer is feasible and does identify potentially actionable targets, in most cases amplification of known oncogenes such as ERBB2, EGFR, FGFR1–3, KRAS and MET, in a significant proportion of patients." (PMID 34794033, 2021). "In addition, FGFR1 was expressed on iCAFs and ECs, while FGFR3 was expressed on tumor cells." (PMID 33033240, 2020). "FGFR1 accelerates tumor development without forcing cells toward a particular tumor subtype." (PMID 31910904, 2020). "Notably, several multi-kinase inhibitors, including dovitinib (FLT-3/c-Kit, FGFR1/3, and VEGFR) and cediranib (VEGFR, FIT1/4, and c-KIT), showed significantly high anti-tumor activities in HGSCs (P = 2.92 × 10−02 and P = 3.98 × 10−03 for dovitinib and cediranib, respectively)." (PMID 31771620, 2019). "To determine if the FGFR inhibitor could overcome FGFR1-mediated effects in vivo, we implanted MCF-7eGFP and MCF-7FGFR1 cells in ovariectomized athymic mice supplemented with a 14-day release 17β-estradiol pellet to support initial tumor establishment." (PMID 30914635, 2019). "In the FGFR1-amplified lung cancer cell line H1581-xenograft mice and FGFR2-amplified GC cell line SNU16-xenograft mice, oral administration of SOMCL-085 for 21 days substantially inhibited tumor growth without loss of body weight." (PMID 31242658, 2019). "Among the tumor-related genes, the top amplified genes included ERBB2 (17q21), MYC (8q24), GNAS (20q13), EGFR (7p11), ZNF217 (20q13), CCNE1(19q12), NCOA3 (20q13), and CDK6 (7q21), and the most frequently deleted genes were CDKN2A (9p21), CDKN2B (9p21), KIT (4q12), SMAD4 (18q21), and FGFR1 (8p12)." (PMID 31541076, 2019).
tumor (continued). "In agreement with the role of FGFR1 in promoting cell proliferation and carcinogenesis, a number of iFGFR1-upregulated genes are cancer-driving genes such as ETS1, PIM1, NRG1, MMP1, and FOXQ1, while some iFGFR1-downregulated genes are tumor suppressors such as NR4A1 and GDF15." (PMID 30111373, 2018). "FGFR1 controls glucose uptake and utilization by activating the AKT/mTOR pathway, which in turn in involved in the induction of GLUT-1 glucose transporter expression; FGFR inhibitors exert their anti-tumor activity also through the inhibition of glucose metabolism through AKT/mTOR inhibition." (PMID 30060526, 2018). "The results suggest that FGFR1-activated PI3K/AKT/mTOR and JAK/STAT3 signaling pathways may promote NB development and ponatinib-induced inhibition of FGFR1 signaling contributes to its anti-tumor effects." (PMID 27564113, 2017). "Since ponatinib targets several tyrosine kinases and only FGFR1-activated PI3K/AKT/mTOR and JAK/STAT3 signaling pathways have been investigated in this paper, it is highly likely that the inhibition of other targets also contributed to ponatinib-induced anti-tumor effect in NB." (PMID 27564113, 2017). "Similarly analysis of FGFR1 protein expression by IHC revealed a range of overlapping expression levels in amplified and non-amplified tumours." (PMID 26905262, 2016). "FGFR1 protein expression by IHC revealed a similar pattern of overlapping expression levels between the amplified and non-amplified tumour samples, although while FGFR1 protein was undetectable in 68% (30/44) of the non-amplified tumours this was the case for only 9% of the amplified cancers (1/11)." (PMID 26905262, 2016). "As observed for early S115 lesions, treatment with ARPCA (i.p. at 100 mg/kg every other day) impaired FGFR1 activation in TRAMP-C2 alginate plugs, thus leading to a decrease of the tumor cell proliferation rate (as assessed by Ki67 immunostaining) and of CD31-positive tumor vascularization." (PMID 25912421, 2015). "Thus, we asked whether these pathways are operational in tumor cells by examining the anosmin-1-induced motility in the presence of specific inhibitors of FGFR1 (SU5402, FGFR1 ectodomain antibody) or uPA (amiloride, uPA antibody)." (PMID 24189182, 2014). "Furthermore, significantly increased Fgfr1 mRNA expression was described in functioning tumors that invaded the sphenoid bone compared with those that did not, thus raising the possibility of using the FGFR1 as a molecular marker of tumor biological behavior." (PMID 25505910, 2014). "Inhibition of FGFR signaling with either BGJ-398 or FGFR1 knockdown resulted in strong suppression of invasion in vitro, and BGJ-398 blocked CTC production and metastasis (without inhibiting primary tumor growth) in mice inoculated with orthotopic, FGFR1-positive UM-UC3 tumors in vivo." (PMID 23468956, 2013). "Four cases showed gains of FGFR-1 gene signals in the metastases and not in the primary tumours." (PMID 23270564, 2012). "Moreover, by analyzing FGFR1 mRNA expression, a stromal-rich tumor subtype has been identified that lacks both KRT5 and KRT20 mRNA expression and is almost resistant to upfront chemotherapy (0% pCR rate in FGFR1 high tumors vs. 66.7% pCR rate in FGFR1 low tumors)." (PMID 35887247, 2022). "Besides having a membrane localization-associated decoy function, which could primarily function in normal cells and tissues, FGFRL1 may, in a tumor tissue context, contribute to PCa progression by other modes of action, such as an FGF-binding-dependent co-receptor function via FGFR1." (PMID 35053442, 2022).
tumor (continued). "However, we also found that the mRNA levels of Fgfr3 in the Renca model and Fgfr1 and Fgfr4 in the B16F10 model were significantly upregulated by chronic expression of VEGFR2-Fc, consistent with previous reports that FGFR1, 3, and 4 also play a critical role in tumor angiogenesis." (PMID 32076044, 2020). "Indeed, FGFR1 has been shown to directly phosphorylate pyruvate kinase M2 (PKM2), a key enzyme of glycolysis, allowing its switching towards a less active dimeric form and therefore enhancing the use of glycolytic intermediates for macromolecular biosynthesis and tumor growth." (PMID 29190880, 2017). "However, there was significant overlap in FGFR1 expression between the amplified and non-amplified cohort, with several non-amplified tumours observed to have expression levels equivalent to those of the amplified tumours." (PMID 26905262, 2016). "We evaluated FGFR1 expression in the established PDX tumor models by western blot and found markedly increased FGFR1 expression in AB740 which showed high level FGFR1 amplification (8 copies) compared to the tumors without FGFR1 copy number gain." (PMID 41202566, 2025). "Selective inhibition of tumor cell lines featuring active FGFR signaling was observed, distinguishing it from cell lines lacking FGFR aberrations (FGFR1, 2, and 3)." (PMID 38282676, 2023). "Together, our results strongly support that FGFR1, but not FGFR2, promotes tumor invasion in GBM, linking spatial distribution of receptor expression within GBM to function on cell motility." (PMID 37579831, 2023). "We found FGFR1 expressed in tumor mass and infiltrating GBM cells, while FGFR2 expression is confined to the tumor mass and notably absent in diffusely invasive cells." (PMID 37579831, 2023). "The differential expression of FGFR1/FGFR2 in invasive GBM cells is reflected in the functional consequences of FGFR1 and FGFR2 knockdown, as only ablation of FGFR1, but not of FGFR2, reduced GBM cell migration and tumor invasion." (PMID 37579831, 2023). "In addition, FGF2 and p-FGFR1 were highly expressed in FAPα+ HSCs in the co-opted sinusoidal blood vessels in bevacizumab-resistant HCT116 and HT-29 CRCLM xenografts, indicating that tumor cell–derived FGFBP1 might induce FAPα expression in HSCs by activating the FGF2/FGFR1 signaling pathway." (PMID 35951441, 2022). "They discovered that the combination of FGFR1–4 was substantially more expressed in ATC than in normal thyroid, but that leukocytes infiltrating the tumor did not express FGFR1–4." (PMID 36290887, 2022). "No responses were observed in this study and there was no apparent relationship between best tumor response and the presence of FGF2 and FGFR1 protein overexpression or FGFR1 gene amplification." (PMID 34204560, 2021). "Phosphorylation of FGFR1/2 in KM12(Luc) is undetectable by using western blot (data not shown), indicating that the anti-tumor effect of AZD4547 is a consequence of inhibition of TRKA/B rather than FGFR." (PMID 34790577, 2021). "Immunofluorescence of FFPE sections derived from PDX tumours (GCRC1886 and GCRC1915) revealed that MET and FGFR1 are not mutually exclusive and that both RTKs are expressed in the same tumour cells." (PMID 33772015, 2021). "Recent studies have indicated specificity of FGF21 for FGFR1-KLB in adipose tissue, and that the administration of rFGF21 to obese and diabetic patients does not stimulate tumor growth." (PMID 31408968, 2019). "Although, the majority of tumor samples showed no CNA of ALK, PDGFRA, VEGFR2/KDR, FGFR1, and to a lesser extent of MET in both primary and recurrent samples, the concordance of CNA status varied substantially in the subset of cases with alterations." (PMID 30894200, 2019). "We also found that high expression of FGFR1 was correlated with TNM stages, lymph nodes metastasis, and distant metastasis or recurrence, but not correlated with gender, age, and tumor size." (PMID 30484492, 2018).